AXL (AXL receptor tyrosine kinase)
Diseases named in the same sentence as AXL in open-access papers (continued):
Sharing a sentence is not in itself a finding about the gene and the disease.
mesothelioma (continued). "AXL is mainly activated through auto-phosphorylation of its intracellular tyrosine kinase domain, thus inducing PI3K/AKT and Wnt signaling in mesothelioma, AKT phosphorylation levels are significantly downregulated after AXL signaling is inhibited in mesothelioma or metastatic breast cancer." (PMID 34123800, 2021). "About 24.7% of mesothelioma patients in the TCGA dataset were in the AXL high expression group." (PMID 32992696, 2020). "Furthermore, using the TCGA mesothelioma dataset, we analyzed the prognostic value of AXL expression in mesothelioma patients." (PMID 32992696, 2020). "High AXL expression in mesothelioma was correlated with reduced overall survival (p < 0.0001)." (PMID 32992696, 2020). "Our previous reports implicate AXL overexpression, activation, and regulation of downstream intermediates including PI3K/AKT/mTOR and RAF/MAPK in mesothelioma tumorigenesis." (PMID 32992696, 2020). "Our published data have demonstrated that AXL is activated and overexpressed in mesothelioma cell lines (MESO924, MESO296, MESO257, and MESO428) and mesothelioma tumor tissues." (PMID 32992696, 2020). "We showed that ROS induce the phosphorylation of AXL, which was blocked by the selective inhibitor BGB324 in VMC40 and P31 mesothelioma cells." (PMID 29375377, 2017).
mesothelioma (continued). "These in silico analyses demonstrate that the MST1R and TYRO3 receptors are significantly overexpressed in mesothelioma, confirming previous data regarding MET and AXL, and suggesting that all four receptors may be candidate targets for therapy in MPM." (PMID 30863365, 2019). "Our previous published data had demonstrated overexpression and activation of AXL in mesothelioma cell lines and biopsy materials, which regulates tumor proliferation via PI3K/AKT/mTOR and RAF/MAPK signaling pathways, and AXL expression was stronger in mesothelioma than in the other tumor types." (PMID 32992696, 2020).
metastatic melanoma (8 papers, 2017 to 2025). A melanoma that has spread from its primary site to another anatomic site. "Overall, AXL was shown to be primarily expressed in metastatic melanoma cells, making AXL an interesting target for therapy." (PMID 35332208, 2022). "In line with this, AXL inhibition in combination with PD-1 inhibitor pembrolizumab is currently in phase Ib/II clinical trial for treatment of metastatic melanoma (NCT02872259)." (PMID 31917795, 2020). "A phase II randomised discontinuation trial assessed cabozantinib (XL184), an orally bioavailable inhibitor of tyrosine kinases including VEGF receptors, MET, and AXL, in a cohort of patients with metastatic melanoma." (PMID 28103611, 2017). "Overall, these data suggest that targeting the VEGFR, MET, and AXL pathways with cabozantinib may lead to improved outcomes in patients with metastatic melanoma." (PMID 28103611, 2017). "Critically, FRA1 directly activates AXL, CDK6, and FSCN1, which are upregulated in metastatic melanoma and correlate with poor patient outcomes." (PMID 41286309, 2025). "Together this makes AXL a promising target in stage III and metastatic melanoma." (PMID 35332208, 2022). "Since metastatic melanoma is a heterogeneous disease, we stratified metastatic melanoma samples into MITFhigh/AXLlow and MITFlow/AXLhigh groups based on their relative MITF and AXL levels." (PMID 37849907, 2021).
Arthritis (7 papers, 2017 to 2024). Inflammation of a joint. "In summary, we describe herein that miR-34a controls AXL, a tyrosine kinase receptor that governs the termination of DC activation and contributes to the development of experimental arthritis." (PMID 28639625, 2017). "Furthermore, studies revealed that targeted delivery of TAM receptor ligand genes Gas6 diminishes the arthritis pathology effectively but the endogenous role of AXL in arthritis development is not fully understood." (PMID 34841689, 2022). "Moreover, AXL plays a protective role in experimental arthritis, possibly by regulating the post-translational activation of IL-1β (manuscript accepted for publication)." (PMID 30335822, 2018). "We found a negative-feedback control of DC activation, mediated by miR-34a governing immunosuppressive AXL pathway activation, that is aberrant in circulating, SF and synovial tissue CD1c+ DCs of RA patients; and that also contributes to experimental arthritis." (PMID 28639625, 2017).
gastrointestinal stromal tumor (7 papers, 2010 to 2023). "Elevated level of AXL expression and its activation have been implicated in the resistance to imatinib in gastrointestinal stromal tumors (GIST)." (PMID 37469409, 2023). "In gastrointestinal stromal tumors (GIST) and other cancer types, AXL overexpression has been associated with intrinsic or acquired resistance to targeted therapies, as well as to chemotherapy and radiotherapy." (PMID 35886842, 2022). "Furthermore we evaluated the gene expression of KIT as well as the alternative RTK FLT3, CSF1-R, PDGFRB, AXL and MET in mutated and non-mutated gastrointestinal stromal tumors by qPCR using the identified reference genes." (PMID 21171987, 2010).
liver fibrosis (7 papers, 2019 to 2025). "Some metalloproteinases such as ADAM10/17 cut the extracellular domain of AXL and release into blood in the form of soluble AXL, which was confirmed to be an accurate biomarker of advanced liver fibrosis, cirrhosis and HCC14." (PMID 39897049, 2025). "Soluble AXL (sAXL) has recently been utilized as a serum biomarker for liver fibrosis and cirrhosis, and has been associated with CKD." (PMID 37813528, 2023). "Lastly, the key differential ligand-receptor pairs involved in cellular communications were identified and we confirmed the role of GAS6_AXL interaction-mediated cellular communication in promoting liver fibrosis." (PMID 36814339, 2023). "In the context of liver fibrosis, the soluble extracellular domain of AXL is cleaved and released into the circulation where it is an accurate biomarker to detect advanced liver fibrosis and cirrhosis." (PMID 35158733, 2022). "Therefore, at present, TAM receptors, including AXL, are considered as key targets for treating liver fibrosis." (PMID 38069259, 2023). "Therefore, we experimentally confirmed the potential contributing role of the GAS6_AXL pair in TCS-induced liver fibrosis, thus leading to increased expression of α-SMA." (PMID 36814339, 2023). "Indeed, advanced liver fibrosis characterized by inflammation, injury, and hepatic fibrosis predisposes patients to HCC, suggesting that AXL can be an oncogenic driver in this context." (PMID 35158733, 2022). "The GAS6/AXL signaling pathway regulates HSC proliferation and activation, which play an important role in liver fibrosis development." (PMID 38069259, 2023). "In mice, interfering with AXL functions reduced HSC activation, liver fibrosis and inflammation, and prevented development of NASH." (PMID 35158733, 2022). "A study on liver fibrosis showed that AXL and GAS6 are required to induce fibrogenesis by hepatic stellate cells; Accordingly, exposition to bemcentinib reduced liver fibrosis in mice." (PMID 31134766, 2019). "The GAS6/AXL pathway promotes HSC activation and could attenuate hepatic fibrosis." (PMID 37108648, 2023).
metastatic carcinoma (7 papers, 2016 to 2022). A carcinoma which has spread from the original site of growth to another anatomic site. "While studies have shown the benefits of AXL inhibition for the treatment of metastatic cancers, additional roles for AXL in cancer progression are still being explored." (PMID 35158733, 2022). "A miR34a target site was identified within the AXL 3′-UTR where it binds and inhibits AXL expression in metastatic cancer cell lines." (PMID 27834845, 2016). "In line with our previous findings, pharmacological inhibition of AXL after gemcitabine withdrawal significantly reduced metastatic relapse, AXL (pAXL) activation and proliferation (Ki67+) of metastatic cancer cells, while immune cell infiltration remained unaffected." (PMID 35022267, 2022). "Because AXL is emerging as a promising drug target to limit certain metastatic cancers including TNBC, we sought to identify drugs that could be repurposed based on their induction of a gene signature similar to that seen with AXL depletion." (PMID 31007848, 2019). "The AXL receptor tyrosine kinase (AXL), which is expressed in tumor cells, plays an essential role in the resistance of cancers to chemotherapy and immunotherapy, and stimulates signaling associated with epithelial-mesenchymal transition (EMT) in metastatic cancer." (PMID 35356198, 2022).
metastatic disease (7 papers, 2014 to 2025). "Observations that AXL expression leads to an increased risk for metastatic diseases is supported by previous works showing that AXL-mediated pathways in MM may drive and sustain cell migration, invasion, and drug resistance." (PMID 34745951, 2021). "In epithelial ovarian cancer, AXL was over-expressed in the advanced metastatic tumors compared to the low grade tumors." (PMID 25551830, 2014). "Beyond its role in immune suppression, AXL is also implicated in EMT and cancer stemness, suggesting that inhibiting AXL could provide insights into these processes in metastatic disease and their impact on chemosensitivity and resistance." (PMID 39924521, 2025). "A better understanding of AXL’s role in these processes could lead to new therapeutic approaches that would benefit patients suffering from metastatic diseases." (PMID 35158733, 2022).
neuroblastoma (7 papers, 2016 to 2025). Neuroblastoma (NB) is the most common solid, extracranial childhood tumor. "Altogether, our data support the further development of AXL-targeted ADCs in MES-dominant neuroblastoma models." (PMID 39825754, 2025). "After doxycycline-inducible AXL overexpression in neuroblastoma cell lines, we observed subtle changes in the IMR5 model whereby some MES markers slightly increased and some ADRN markers slightly decreased, supporting AXL as a contributor to the MES subtype." (PMID 39825754, 2025). "Together, these data and our in vitro data suggest that AXL is present in both neuroblastoma cells and cell populations within the tumor microenvironment." (PMID 39825754, 2025). "To assess the functional role of AXL on tumor cells, we modulated its expression in neuroblastoma cell line models and monitored the impact on subtype-specific markers." (PMID 39825754, 2025). "For AXL, we examined the cytotoxicity of bemcentinib, cabozantinib, NPS-1034, and ONO-7475 in a panel of ADRN and MES neuroblastoma cell lines." (PMID 39825754, 2025). "Additionally, studies incorporating heterogenous tumors with combination strategies will be necessary to credential AXL as an effective therapy for the elimination of MES-specific neuroblastoma tumor cells and/or the treatment-resistant neuroblastomas." (PMID 39825754, 2025). "The cytoprotective role of AXL has been recognized in different tumor types, including non-MYCN–amplified neuroblastoma." (PMID 32962733, 2020).
ovarian tumors (7 papers, 2011 to 2025). "Metastatic ovarian tumor cells are critically associated with the GAS6/AXL signaling pathway for metastatic colonize." (PMID 31700829, 2019). "METTL3 stimulates AXL mRNA translation and epithelial–mesenchymal transition, thereby promoting growth and invasion of ovarian tumors." (PMID 34363020, 2021). "For example, in ovarian tumors, AXL dimerizes with MET, EGFR, and HER2, leading to sustained ERK activation." (PMID 32245042, 2020). "Together, these findings suggest that therapeutic blockade of AXL signaling may be an effective strategy for ovarian tumors with PIK3R2 amplification." (PMID 32385243, 2020). "Receptor EGFR, ERBB2, MET, and AXL were strongly co-activated in most primary ovarian tumors." (PMID 21962244, 2011). "In metastatic ovarian tumor cells, AXL expression is dramatically increased and accumulating of these cells to form colony is noticeably depend on the GAS6/AXL signaling pathway." (PMID 31700829, 2019).
Alzheimer disease (6 papers, 2016 to 2026). A progressive, neurodegenerative disease characterized by loss of function and death of nerve cells in several areas of the brain leading to loss of cognitive function such as memory and language. "In the research on Alzheimer’s disease (AD), it was found that the AXL/ERK signaling pathway is involved in the proliferation and phenotypic transformation of microglia." (PMID 36408274, 2022). "Indeed, CSF and serum levels of soluble AXL (sAXL) have been correlated with neurodegeneration and cognitive decline in Alzheimer's disease (AD)." (PMID 41919222, 2026). "However, the tyrosine kinase family receptors have been studied in Alzheimer’s disease, wherein the soluble ectodomain of AXL receptor tyrosine kinase, released following AXL activation, demonstrated predictive value for Alzheimer’s disease development." (PMID 38397929, 2024). "In addition, AXL regulates APOE9, a key protein and risk factor gene in Alzheimer’s pathogenesis, and both MERTK and AXL are co-expressed with TREM210, another genetic risk factor gene for Alzheimer’s disease (AD)." (PMID 40596721, 2025).
autoimmune disease (6 papers, 2019 to 2025). A disorder resulting from loss of function or tissue destruction of an organ or multiple organs, arising from humoral or cellular immune responses of the individual to their own tissue constituents. "For all three TAM receptors, RIP is caused by γ-secretase (for AXL, MER, TYRO3) or MMP2 (for TYRO3) (see“sTAM and autoimmune diseases”)." (PMID 40044635, 2025). "TAM (TYRO3, AXL, MER) is a family of RTKs implicated in cancer and autoimmune disorders, for which ED shedding and RIP were reported." (PMID 40044635, 2025). "Axl receptor tyrosine kinase and its ligand Gas6 regulate several biological processes and are involved in both the onset and progression of tumor malignancies and autoimmune diseases." (PMID 38276597, 2024). "Studies of AXL expression in tumor and autoimmune diseases revealed that AXL is regulated by a variety of miRNAs, including miR-34a, miR-199a, and miR-92b." (PMID 34734092, 2021).